NAMPT (nicotinamide phosphoribosyltransferase)
Diseases named in the same sentence as NAMPT in open-access papers (continued):
Sharing a sentence is not in itself a finding about the gene and the disease.
cancer (continued). "NAMPT and NAPRT, as rate-limiting enzymes in these two pathways, play a crucial role in the occurrence and development of cancer." (PMID 35906622, 2022). "Cancer cells require high amounts of energy to support their proliferation, implying an increased demand for NAD through NAMPT overexpression to fund cellular metabolism and NAD depletion responses." (PMID 35906622, 2022). "Nicotinamide phosphoribosyl transferase (NAMPT) is the rate-limiting enzyme for NAD+ salvage and is overexpressed in several cancers." (PMID 35814452, 2022). "In addition, rather than being mutated, the NAMPT gene was found amplified in cancer." (PMID 36077374, 2022). "First of all, due to the characteristics of high metabolism in the tumor microenvironment, NAMPT, a rate-limiting enzyme of NAD synthesis, is generally considered to play a major role in promoting cancer." (PMID 35906622, 2022). "NAMPT is known to be a poor prognosis marker and a known drug target for the NAD pathway in many cancers, and we tested if the levels of this gene had any prognostic value." (PMID 36249025, 2022). "To further confirm the observed sensitization effect of our putative inhibitors on the anti-tumor activity of NAMPT inhibitors, we extended our experiments in two additional NAPRT-expressing cancer cell lines (i.e., HCT116 and OVCAR-8)." (PMID 35890147, 2022). "FK866 is the most effective NAMPT inhibitor developed to date and is used extensively in cancer research to target NAD+ synthesis and prevent cancer cell proliferation." (PMID 35397003, 2022). "Nicotinamide phosphoribosyltransferase (NAMPT) is a rate-limiting enzyme in the NAD salvage pathway of mammalian cells and is overexpressed in numerous types of cancers." (PMID 36160449, 2022). "In this two-step pathway, the reaction of NAMPT is mainly the rate-limiting step, and the high levels of NAD are observed in many chemotherapy-resistant cancer cells due to over-expression of the corresponding enzyme." (PMID 35335372, 2022). "Numerous genes, associated with NAD+ biosynthesis and metabolism, have been identified as promoting tumor development, for example, NAMPT, nicotinic acid phosphoribosyl transferase, NADK, which makes them promising targets in cancer therapy." (PMID 35595095, 2022). "To identify parameters that could negatively affect the therapeutic efficacy of NAMPT inhibitors and propose therapeutic strategies to circumvent such failure, we performed metabolomics analyses in tumor environment and explored the effect of the interaction between microbiota and cancer cells." (PMID 35396381, 2022). "NAMPT inhibitors such as FK866, GMX1777, and GMX1778, have been developed as a candidate novel therapeutic strategy for cancer." (PMID 33912035, 2021). "SIRT6 is regulated by deacetylation nicotinamide phosphoribosyltransferase (NAMPT) activity and restores NAD(P)(H) pools in cancer cells." (PMID 33440786, 2021). "For example, over-expression of NAMPT, the rate-limiting factor for NAD+ synthesis in mammalian cells, is frequently observed in a number of malignant tumors including breast, colorectal, ovarian and prostate cancers." (PMID 34095234, 2021). "For example, it has been shown that in cancer cells that lack NAPRT expression and in which NAD synthesis solely depends on NAMPT, NAMPT inhibitors are significantly more potent." (PMID 32477131, 2020). "In vitro studies have shown promising results using a NAMPT inhibitor in cancer cells, especially the IDH1/2 mutant cancer cell lines." (PMID 32111066, 2020). "Accordingly, Nampt (nicotinamide phosphoribosyltransferase), a rate-limiting enzyme for NAD synthesis in mammalian cells, is frequently amplified in cancer cells." (PMID 33008042, 2020). "Conversely, NAMPT-specific inhibitors significantly deplete NAD levels and subsequently suppress cancer cell proliferation." (PMID 32111066, 2020). "Furthermore, NAMPT is frequently amplified in some cancers which may also affect the NAD pool." (PMID 32111066, 2020).
cancer (continued). "NAMPT inhibitors, FK866, STF-118804 and KPT-9274, can reduce the viability and growth of different cancer cells and have an additive effect in combination with main current chemotherapeutic drugs." (PMID 33028824, 2020). "Nicotinamide phosphoribosyl-transferase (NAMPT), the rate-limiting enzymes for NAD+ synthesis, induces cancer stem cell phenotype through SIRT1 activation." (PMID 33339101, 2020). "The inhibition of NAMPT and NAPRT sensitizes cancer cells to DNA damage, such as DSB-inducing drugs or alkylating agents." (PMID 32722390, 2020). "In conclusion, we first investigated the clinicopathological and prognostic value of NAMPT and NAPRT in cancer and adjacent tissues from 261 CRC patients." (PMID 31448236, 2019). "Among the enzymes involved in NAD homeostasis, NAMPT, CD38, sirtuins, and IDO are overexpressed in different types of cancer and have been shown to play a role in cancer immune tolerance." (PMID 31402913, 2019). "A previous study has shown that NAMPT and NAD energy metabolism play an important role in cancer progression." (PMID 31817697, 2019). "Thus, miRNAs may be responsible for the dysregulation of NAMPT levels in cancer." (PMID 31645844, 2019). "Inhibition of NAMPT by specific inhibitors, such as FK866, or its down-regulation by siRNA reduces intracellular NAD+ levels and decreases cancer cell growth." (PMID 30856230, 2019). "In multiple cancer models, a decrease in phospho-ERK1/2 was observed with NAMPT inhibition and combining NAMPT inhibitors with ERK1/2 blockade enhanced cell death." (PMID 32010616, 2019). "NAD is a co-enzyme that controls the redox reactions in several metabolic pathways, including glycolysis through the nicotinamide phosphor-ribosyltransferase (NAMPT), a rate-limiting enzyme for the NAD synthesis frequently overexpressed in cancer cells." (PMID 31750245, 2019). "Our present study detected NAMPT and NAPRT protein expression in cancer and adjacent tissues from 261 CRC using immunohistochemical staining." (PMID 31448236, 2019). "Inhibition of NAMPT by specific inhibitors, such as FK866, or its down-regulation by siRNA reduces intracellular NAD+ level and decreases cancer cell growth in both in vitro and in vivo models." (PMID 30856230, 2019). "The NAMPT inhibitor, APO866 has been used in Phase II clinical trials against several human cancers." (PMID 30283496, 2018). "NAMPT is the key biosynthetic enzyme involved in NAD+ generation and recycling in cells and is a compelling anti-cancer drug target." (PMID 29100430, 2017). "We investigated the metabolic and mechanistic processes that regulate PARP-1-mediated CTCF PARylation in human cancer cell lines and discovered a key role for the expression and activity of β-NAD+ salvage enzymes, NAMPT and NMNAT-1." (PMID 29029387, 2017). "NAMPT is essential for biosynthesis of NAD and has been found to be upregulated in many cancer cells." (PMID 29245920, 2017). "Nicotinamide phosphoribosyltransferase inhibitors (NAMPTis) inhibit NAD+ biosynthesis and represent promising new anti-cancer agents." (PMID 29100430, 2017). "NAMPT is the rate-limiting enzyme in the biosynthesis of NAD+ from nicotinamide, thereby providing cancer cells with one of the key metabolites essential for sustaining energy metabolism." (PMID 28086232, 2017). "NAMPT is a fascinating target for the chemotherapeutic treatment of PDAC for a number of reasons Firstly, the recycling of NAD+ is vital for cancer cells due to a high need of ADP ribosylation to repair DNA, preserve genome stability, and maintain telomeres." (PMID 27462772, 2016). "As cancer cells have increased NAD requirements, the main NAD salvage enzymes in humans, nicotinamide phosphoribosyltransferase (NAMPT) and nicotinate phosphoribosyltransferase (NAPRT), are involved in the development of novel anti-cancer therapies." (PMID 26675378, 2016).
cancer (continued). "Using our experimental assay directly targeting NAMPT, we identified a highly potent NAMPT inhibitor MS0 and demonstrated its activity against multiple human cancer cell lines, which was granted with China Patent ZL201110447488.98." (PMID 26040985, 2015). "The NAMPT enzymatic inhibitor, FK866, acts as an inducer of apoptosis and is a cancer therapeutic candidate, however, little is known regarding the influence of NAMPT on cancer biological mechanisms or on the prognosis of human cancers." (PMID 25146220, 2014). "Since the cytotoxic effect is activated upon successful binding between NAMPT and FK866/APO866, the utilization of FK866/APO866 as an anti-cancer agent has its limitation." (PMID 24690091, 2014). "A recent study identified a positive feedback loop consisting of MYC, the nicotinamide-phosphoribosyltransferase (NAMPT) enzyme, the SIRT1 inhibitor deleted in breast cancer 1 (DBC1) and SIRT1." (PMID 24884974, 2014). "All the down-regulated genes, in this Panel 3 showed their significant up-regulation in most of many types of cancers (TGM2, CSNK1A1, CTNNA1, NAMPT/Visfatin, TNFRSF1A, ETS1, SRC-1, FN1, APLP2, DMBT1/SAG, AIB1, AZIN1)." (PMID 23122428, 2012). "We also discuss the potential of NAMPT as a therapeutic target, particularly through NAD+ precursor supplementation or the use of NAMPT activators and inhibitors to modulate NAD+ metabolism in aging, metabolic diseases, and cancer." (PMID 40775221, 2025). "For instance, nicotinamide phosphoribosyl transferase (NAMPT) is a rate-limiting enzyme for mammalian NAD+ synthesis, and NAMPT inhibitors have been shown to reduce NAD+ levels as well as induce cell death in various cancers." (PMID 41009660, 2025). "Inhibition of both NAMPT and CD73 has been shown to reduce cancer cell proliferation." (PMID 38399441, 2024). "One additional advantage of NMNAT inhibition compared to either NAMPT or NAPRT blockades is that cancer cells would not be able to adapt to NMNAT inhibition through alternative NAD+-producing routes." (PMID 38396769, 2024). "In these instances, administering NAMPT inhibitors in combination with NA is postulated to help many healthy, NAPRT-proficient tissues, but not NAPRT-deficient cancer cells in avoiding the consequences of NAMPT obstruction." (PMID 38396769, 2024). "In this review, we will describe the relevance of these NAD+-producing enzymes as potential targets in cancer, mainly focusing on the reported molecules that inhibit the activity of NAD+-producing enzymes other than NAMPT (which has been extensively covered in other recent articles)." (PMID 38396769, 2024). "Cancer cells primarily depend on the salvage pathway to produce the NAD+ they need for their proliferation and survival, and thus, they are expected to be vulnerable to NAMPT inhibition." (PMID 38396769, 2024). "NAMPT and INSR are potential therapeutic targets in multiple cancer types and may be crucial in suppressing CSCs." (PMID 39107908, 2024). "Based on clinical data, we demonstrated a negative correlation between the expression of NAMPT and PD-L1 expression in various cancer cell lines, and NAMPT and PD-L1 are co-expressed in various human cancers." (PMID 38448544, 2024). "It has been further suggested that the increased enzymatic activity of NAMPT may result from the rapid proliferative rate and the shorter half-life of NAD in cancer cells." (PMID 39452130, 2024). "Several NAMPT inhibitors, such as FK866, GMX1778, CHS828,130 and OT-82,124 have been developed and are currently undergoing clinical trials to assess their efficacy in treating various types of cancer." (PMID 38988322, 2024). "As one of the reasons of the failure, it’s been indicated that some cancers are not NAMPT-dependent." (PMID 38424218, 2024). "This question is especially pertinent given the role of NAD+ in maintaining cancer cell metabolism, and the development of NAD+ biosynthetic inhibitors targeting nicotinamide phosphoribosyltransferase (NAMPT) to treat cancer." (PMID 39169162, 2024).
cancer (continued). "Our results showed that NAMPT and PD-L1 (CD274) are highly expressed in most cancers." (PMID 38448544, 2024). "In particular, it raises the question of whether it inhibits cancer cell growth via PAK4 inhibition, NAMPT inhibition, or both." (PMID 39337621, 2024). "Studies has shown that NAMPT inhibition induces cytotoxicity in cancer cell lines, but not in non-cancer cells in vitro." (PMID 38424218, 2024). "Notably, the amplification of nicotinamide phosphoribosyltransferase (NAMPT), the rate-limiting enzyme in NAD synthesis, underscores its pivotal role in sustaining NAD-dependent metabolic pathways essential for cancer cell survival." (PMID 39336077, 2024). "This resistance can be reversed through gene silencing or direct inhibition of NAPRT, suggesting that co-administration of NAPRT and NAMPT inhibitors might represent a successful therapy to decrease NAD levels, leading to cancer cell death." (PMID 37259338, 2023). "In the same cancer cell lines, we did not observe a substantial correlation between the response to A4276 and NAMPT level." (PMID 37771778, 2023). "In addition, the combination of NAMPT and CD73/38 inhibition synergistically reduced intra-cancer levels of NAD+, NMN, ATP, decreased the proliferation of ovarian carcinoma cells in vivo and improved the survival of animals with cancers." (PMID 37175631, 2023). "For example, reduction of intracellular levels of the PARP substrate NAD+ via inhibition of nicotinamide phosphoribosyltransferase (NAMPT) or high levels of the NAD+ derivative NADP+ reduce PARP activity and thereby enhance sensitivity of cancer cells to PARPis." (PMID 37209095, 2023). "The distinct binding mode and inhibition kinetic of A4276 compared to other NAMPT inhibitors may account for the discrepancies mentioned, leading to its higher selectivity against NAPRT-negative cancer cells." (PMID 37771778, 2023). "Perhaps these types of drugs are more effective in cancers that do not have high T cell infiltration but overexpress NAMPT." (PMID 37842241, 2023). "Therefore, in cancers with low-NAPRT expression, inhibition of NAMPT is a potential therapeutic approach." (PMID 37771778, 2023). "Hence, exploring the impact of NAMPT on the EMT and stemness in cancer cells can pave the way for the clinical application of NAMPT inhibitors, PARP inhibitors, and SIRT inhibitors." (PMID 38116009, 2023). "Chromatin immunoprecipitation and additional research revealed that this H3K27 acetylated NAMPT enhancer binds to the transcription factors MAX and c-MYC, which control its activity, and performs substantially better exclusively in cancer cells that are dependent on the salvage pathway." (PMID 36160449, 2022). "Many cancer cells upregulate nicotinamide phosphoribosyltransferase (NAMPT), the rate-limiting step for NAD+ salvage; thus efforts have been made to target this pathway with NAMPT inhibitors." (PMID 34981784, 2022). "Moreover, the NAMPT level was found to be elevated in established HCT-116 and SW480 cancer cells resistant to doxorubicin." (PMID 35565188, 2022). "This evidence suggests that the stromal activation promoted by NAD+ inhibition could limit the efficacy of anti-cancer therapies targeting NAD+ biosynthesis, such as NAMPT inhibitors, and could explain their reported limited efficacy in vivo." (PMID 35545049, 2022). "As normal cells are neither affected by metformin nor by FK866 due to a low expression of NAMPT, the effect of the Met+FK combination on cancer cells is expected to be relatively specific." (PMID 36428689, 2022). "Thus, based on our ground-truth dataset, the buffering capacity of the NAMPT and CALD1 gene pair in different tissue/cell types can be used to predict patient survival for specific cancer types." (PMID 35194081, 2022).
cancer (continued). "Many previous studies have reported the cancer‐promoting potential of USP22, including the induction of cell proliferation and DNA repair, activation of c‐Myc/NAMPT/SIRT1‐dependent FOXO1 and YAP signaling, and deubiquitination of CD274 to suppress anticancer immunity." (PMID 34743406, 2022). "NAMPT inhibitors diminish NAD levels and, as a result, hamper the cellular growth of cancer." (PMID 36160449, 2022). "An increase in the levels of NAD+ enhanced the malignant phenotype in the cells and led to poorer outcomes, accompanied by NAMPT overexpression, which is mainly produced by the NAD+ salvage pathway in cancer cells and involved in several pro-cancer pathways mediated by NAMPT." (PMID 36556252, 2022). "Even though inhibiting NAMPT was proposed as a therapeutic strategy for cancer patients, NAMPT (i)nhibitors showed no objective tumor remission in early clinical trials." (PMID 35272691, 2022). "This conclusion was further substantiated by the observation that neither the overexpression of NAPRT in salvage-dependent cancer cells nor the overexpression of NAMPT in PH-amplified cancer cells has reversed their predestined NAD metabolic pathway." (PMID 34068917, 2021). "Additionally, KPT-9274 also inhibits NAMPT activity, subsequently decreasing the NAD/NADH ratio, which eventually prevents the cancer cells from meeting their metabolic needs." (PMID 35008323, 2021). "In addition, NAMPT regulation of cancer stem cell pathways correlated with SIRT1 and PARP1, as these proteins seem to play important roles in the CSC phenotype acquisition promoted by NAMPT." (PMID 33384409, 2021). "In the past years, targeting NAD+ metabolism has been considered for cancer therapy, and most efforts have been focused on nicotinamide phosphoribosyltransferase (NAMPT), the rate-limiting enzyme of the NAD+ salvage pathway, whose expression is increased in multiple types of cancer." (PMID 34919052, 2021). "In addition to PARP and NAMPT, other NAD+ homeostasis factors such as sirtuins and CD38 also play important roles in cancers and other metabolic diseases, which have been extensively discussed in recent reviews." (PMID 34095234, 2021). "NAMPT-specific inhibitors reduce NAD levels by inhibiting energy metabolism pathways, such as glycolysis, TCA, and OXPHOS, contributing to the suppression of cancer cell proliferation." (PMID 34073463, 2021). "We summarize how aberrant alterations of PARG, NAMPT, NQO1, cMET and “BRCAness” genes that have been shown to affect PARP activity in cancers could serve as prognostic biomarkers for targeted therapy." (PMID 32295316, 2020). "On the other hand, DHPS expression appeared to correlate positively with sensitivity to other agents, such as NAMPT, BCL2, and MDMX inhibitors, indicating that DHPS level can be used as a predictive biomarker for response to several different anti-cancer agents." (PMID 32989218, 2020). "Nicotinamide phosphoribosyl transferase (NAMPT), which is a rate-limiting enzyme for NAD+ synthesis in the salvage pathway, was shown to be overexpressed in many types of cancer, suggesting that NAMPT acts as a regulator of cancer invasion and metastasis." (PMID 33392072, 2020). "The molecular mechanisms that dictate the choice of the NAD synthesis pathway (NAPRT and/or NAMPT) in normal or cancer cells is still not clear." (PMID 32477131, 2020). "From a different angle, it has been recently described in a patent that chemical compounds that inhibit NAPRT activity (including some non-steroidal anti-inflammatory drugs) sensitize cancer cells to NAMPT inhibitors." (PMID 32477131, 2020). "NAMPT mediates the rate-limiting step of the NAD salvage pathway, which maintains cellular bioenergetics and provides a necessary substrate for functions essential to rapidly proliferating cancer cells." (PMID 32908120, 2020).